MT1DP (metallothionein 1D, pseudogene)
Description:
Metallothioneins have a high content of cysteine residues that bind various heavy metals.
Synonyms: MTM
Gene: Transcribed unprocessed pseudogene on chromosome 16 (56,643,725 to 56,644,765, forward strand). Ensembl gene ENSG00000205361.
Diseases named in the same sentence as MT1DP in open-access papers:
MT1DP is named in the same sentence as 11 diseases in open-access papers, as found by Europe PMC text mining. Sharing a sentence is not in itself a finding about the gene and the disease. The quoted sentences say what the papers report.
non-small cell lung carcinoma (6 papers, 2020 to 2023). A group of at least three distinct histological types of lung cancer, including non-small cell squamous cell carcinoma, adenocarcinoma, and large cell carcinoma. "Several recent studies have reported that FRLs affect the development and progression of solid tumors by serving as competing endogenous RNAs, such as OIP5-AS1 in prostate cancer and MT1DP in non-small-cell lung cancer." (PMID 35903713, 2022). "MT1DP loaded by folate-modified liposomes modulates erastin-stimulated ferroptosis of non-small cell lung cancer cells by modulating miR-365a-3p/NRF2 axis." (PMID 34789263, 2021). "Moreover, metallothionein 1D pseudogene (MT1DP) is shown to be a crucial regulator of ferroptosis in non-small cell lung cancer (NSCLC), sensitizing cancer cells to erastin-induced ferroptosis by downregulating NRF2 and enhancing oxidative stress." (PMID 37958383, 2023). "Here we confirmed that MT1DP attenuated expression of NRF2 and increased sensitivity of NRF2-overexpressed non-small cell lung cancer (NSCLC) cells to erastin-induced ferroptosis via stabilizing miR-365a-3p." (PMID 32929075, 2020).
lung cancer (4 papers, 2021 to 2025). A malignant neoplasm involving the lung. "Few studies have explored the biological implications of the pseudogenes harboring the identified CpGs: MT1DP, encoding metallothionein 1 (sub) isoforms, has been reported to have tumor suppressor roles in liver and lung cancers via RNA-RNA interactions." (PMID 35712126, 2022). "lncRNA MT1DP promotes erastin-induced ferroptosis in lung cancer cells via MT1DP/miR-365a-3p/NRF2 signaling." (PMID 36846713, 2023). "MT1DP, a lncRNA, enhances erastin‐induced ferroptosis in non‐small cell lung cancer (NSCLC) by downregulating NRF2 through stabilizing miR‐365a‐3p, leading to increased reactive oxygen species (ROS), malondialdehyde (MDA), ferrous iron, and decreased glutathione (GSH)." (PMID 40556338, 2025). "In lung cancer, lncRNA NEAT1 was proved to be a regulator of ferroptosis sensitivity, and lncRNA MT1DP modulated erastin-induced ferroptosis via miR-365a-3p/NRF2 axis." (PMID 35127813, 2021).
liver cancer (3 papers, 2017 to 2020). An epithelial or non-epithelial malignant neoplasm that arises from the liver. "Mechanistically, YAP and Runx2 together displayed an oncogenic activity by hindering lncRNA MT1DP in a FoxA1‐dependent manner in liver cancer." (PMID 32779318, 2020). "LncRNA MT1DP, a tumour suppressor, could reduce cell proliferation and colony formation, while inducing the apoptosis in liver cancer." (PMID 32779318, 2020). "In liver cancer, YAP/RUNX2 complex binds to the promoter of the tumor suppressor long non-coding (lncRNA) pseudogene MT1DP inhibiting its expression." (PMID 28467351, 2017). "Down-regulation of MT1DP enhances FoxA1 activity with consequent induction of the oncogenic factor AFP, a classic liver cancer biomarker." (PMID 28467351, 2017).
prostate carcinoma (2 papers, 2016 to 2022). A carcinoma that arises from epithelial cells of the prostate gland. "The most frequently altered lncRNAs were DLEU1 and DLEU2, followed by MEG3 and MT1DP, both of which had the alteration frequency >2% in 313 TCGA prostate cancer patients." (PMID 26590405, 2016).
tumor (8 papers, 2016 to 2025). "In vivo, these liposomes effectively inhibit tumor growth, highlighting the MT1DP/miR‐365a‐3p/NRF2 pathway as a promising NSCLC therapeutic target." (PMID 40556338, 2025). "Though less obvious, the most promising tumor suppressor network comprise 4 lncRNAs (MT1DP isoforms (NR_027781 and NR_003658) and MT1IP isoforms (NR_003669 and NR_104046)) that are co-expressed with 8 genes in the metallothionein family." (PMID 32636408, 2020). "Nonetheless, one tumor suppressive network comprising 4 tumour suppressor lncRNAs (MT1DP (seqname: NR_027781 and NR_003658) and MT1IP (seqname: NR_003669 and NR_104046)) and 8 co-expressed genes, enriched in the metallothionein family was identified." (PMID 32636408, 2020). "Opposite to these tumor promotion functions of lncRNAs, the lncRNA metallothionein 1D pseudogene (MT1DP) acts as a tumor suppressor, for its over-expression results in reduced cell proliferation and colony formation in soft agar and increased apoptosis in liver cancer cells." (PMID 26735578, 2016).
infection (4 papers, 2015 to 2022). The state of being infected such as from the introduction of a foreign agent such as serum, vaccine, antigenic substance or organism. "As a result of viral vector-based short hairpin RNA (shRNA) infection, the endogenous MT1DP expression was greatly reduced by approximately 70% in two shRNA transfectants (MT1DP-shRNA1 and 2), here named MT1DPlow cells (P < 0.05)." (PMID 29507753, 2018).
cancer (3 papers, 2020 to 2025). A tumor composed of atypical neoplastic, often pleomorphic cells that invade other tissues. "Additionally, delivering Erastin and lncRNA MT1DP using folate-modified liposomes to enhance NSCLC cell sensitivity to ferroptosis, with MT1DP modulating the miR-365a-3p/NRF2 axis, reducing GSH, and increasing lipid ROS, which promotes ferroptosis and cancer cell death." (PMID 40403492, 2025).
MT1DP also shares sentences with these, for which no sentence is quoted: gastric cancer (1 paper); glioma (1); myopathies (1); rheumatoid arthritis (1).